IL6 (interleukin 6)
Diseases named in the same sentence as IL6 in open-access papers (continued):
Sharing a sentence is not in itself a finding about the gene and the disease.
Hyperglycemia (604 papers, 2005 to 2026). An increased concentration of glucose in the blood. "Our current study revealed a slight inhibitory effect of hyperglycemia on the expression of M2-associated surface markers on macrophages, particularly in IL-6-induced macrophages." (PMID 40429986, 2025). "It was found that the distribution of the IL6 gene’s -174G/C polymorphism was associated with higher levels of HbA1c and hyperglycemia prevalence in individuals with the CC genotype." (PMID 41010061, 2025). "This aligns with research findings indicating that increased IL-6 levels after AP are associated with a higher risk of hyperglycemia." (PMID 41404504, 2025). "More recently, stress-induced IL-6 has been shown to be essential for the acute hyperglycaemia associated with adaptive ‘fight or flight’ responses." (PMID 40275022, 2025). "Persistent hyperglycaemia is associated with elevated levels of pro-inflammatory cytokines, such as interleukin-6 (IL-6) and tumour necrosis factor-alpha (TNF-α), which drive systemic inflammation." (PMID 39338179, 2024). "Hyperglycemia caused a decrease in interleukin 6 (Il-6) and an increase in tumor necrosis factor alpha (Tnf-α), Il-10, F4/80, tumor growth factor beta (Tgf-β), and insulin-like growth factor 1 (Igf-1)." (PMID 36722656, 2023). "Hyperglycemia on admission was correlated with a lower PFR, elevated levels of NLR, CRP, IL-6, and TyG index, while hyperglycemia during hospitalization was associated with increased levels of CRP and TyG index." (PMID 37515156, 2023). "Hyperglycemia is associated with oxidative stress, further triggering DNA damage and facilitating carcinoma.IR induces the expression of IL-6, a pro-inflammatory, and promotes tumorigenesis." (PMID 37370018, 2023). "Inflammation normally affects insulin and glucose metabolism via cytokines such as TNF-α and Interleukin 6, and predispose to hyperglycemia." (PMID 37092113, 2022). "Hyperglycemia has been linked to a pro-inflammatory state leading to increased production of interleukin-6 (IL-6) and tumour necrosis factor α (TNF-α)." (PMID 36463286, 2022). "We found that a flatter DCS was significantly associated with elevated IL-6 levels in the total population (p = 0.008) and the effect was strongest in individuals with hyperglycaemia, even after adjusting for age and sex p = 0.004)." (PMID 34206644, 2021). "Our findings revealed that poststroke hyperglycemia, glucose intolerance, and brain injury were linked to high IL-6 content, and the Jak2 inhibitor AG490 reversed these alterations." (PMID 34943061, 2021). "In trauma patients, on-admission hyperglycemia correlates well with the initial serum IL-6 level and is associated with more severe injuries." (PMID 34117510, 2021). "The expression of the same proinflammatory cytokines implicated in hyperglycemia (IL-6, TNF-α, and CRP) has been reported to be associated with oral infection and PD." (PMID 34068221, 2021). "Our results show that depressed rats induced by 6-week CUMS stimulation display susceptibility to hyperglycemia, which is associated with IL-6-mediated inhibition of glucose homeostasis signaling in the hypothalamus." (PMID 32655424, 2020). "In our study, hyperglycemia was associated with lipid peroxides formation and secretion of proinflammatory cytokines, particularly IL-6, IL-31 and IL-33." (PMID 32824505, 2020). "During the pathogenesis of GDM, the level of pro-inflammatory cytokine TNF-α and IL-6 are elevated by hyperglycemia caused disorder in inflammation and oxidative stress." (PMID 31558153, 2019). "In the present study, STZ-induced rats showed significant loss of body weight, hyperglycemia, insulin deficiency, increased systemic oxidative stress, and elevated inflammatory markers such as Tnf-α and Il-6 in the gingiva 2 months after STZ injection." (PMID 30439990, 2018).
Hyperglycemia (continued). "It has been observed that the diabetic microenvironment can favor NETosis, as in diabetic conditions (hyperglycemia), neutrophils generate oxidative stress and produce cytokines such as IL-6 and TNF-α, which predispose neutrophils to produce ETs." (PMID 28220120, 2017). "Some authors have reported lower or normal levels of this cytokine, but the majority of papers link type 1 diabetes with higher IL-6, which is thought to be associated with prior hyperglycemia and/or progression of microvascular diabetic complications." (PMID 23533301, 2013). "HFFD-induced altered lipid profiles and hyperglycemia are closely associated with elevated pro-inflammatory cytokines, as we recorded increased concentrations of IL-1β, IL-6, and TNF-α." (PMID 23690866, 2013). "More modest increases in IL-6 concentrations are associated with age, hyperglycemia and the physiologic stress of acute exercise." (PMID 22347395, 2012). "In addition to this, we confirmed the association between CC genotype of the C-174G variant of IL-6 gene and hyperglycemia as one of the key symptoms of both MS and T2DM." (PMID 41010061, 2025). "The management of hyperglycemia, with minimal risk of pulmonary complications or fatal outcomes (evidenced by low levels of fibrinogen, C-reactive protein, procalcitonin, and D-dimers), was closely associated with IL-6 levels at the time of hospitalization." (PMID 40134446, 2025). "Longer aortic cross-clamp times may increase inflammatory mediators (e.g., IL-6, IL-8, and IL-10), which can predispose patients to hyperglycemia." (PMID 40260105, 2025). "The IL-6, IL-8 and NF-κB are expressed highly during inflammation associated with hyperglycemia." (PMID 38723008, 2024). "Hyperglycemia, as observed in T2D, is associated with inflammation characterized by elevated levels of proinflammatory cytokines, such as interleukin-6 (IL-6), tumor necrosis factor-alpha (TNF-α), and C-reactive protein (CRP) and these altogether increase the risk of CVD." (PMID 39683570, 2024). "First, stress-induced hyperglycemia is frequently associated with an upregulation of the immune-inflammatory response, leading to an increase in the release of pro-inflammatory cytokines such as interleukin-1, interleukin-6, and tumor necrosis factor-α." (PMID 38824608, 2024). "In addition to lower PFR, elevated levels of NLR, CRP, IL-6, and TyG index were highly associated with an increased incidence of hyperglycemia on admission." (PMID 37515156, 2023). "There is significant concern that current corticosteroid dosing may result in inadequate modulation of IL-6 and IL-10 levels and subsequent treatment failure or in toxicity from steroid-induced hyperglycemia or infection risk." (PMID 37484782, 2023). "It has been demonstrated that hyperglycemia causes the IL-6 and TNF-α increase; through the oxidative mechanism, research on diabetic patients has shown a significant association between IL-6, TNF-α, and diabetic nephropathy that can be used as indicators of diabetic nephropathy." (PMID 35685736, 2022). "Hyperglycemia may also cause diabetic nephropathy through ROS activation, further accelerating the production of inflammatory cytokines such as IL-6 and TNF-α, leading to diabetic nephropathy." (PMID 35685736, 2022). "This response may also contribute to ketoacidosis: interleukin 6 has been implicated in hyperglycemia induced by physiologic stress, and the elevation is even higher in patients with impaired glucose tolerance." (PMID 35718795, 2022). "Hyperglycemia can cause chronic inflammation, promote infiltration of inflammatory cells in renal tissues, and produce large amounts of proinflammatory factors, such as IL-1β, IL-6, and TNF-α." (PMID 36425593, 2022). "It has been proven that hyperglycemia might be responsible for the overproduction of IL-6, which causes a worse prognosis in COVID-19 patients with improperly controlled glycemia." (PMID 33801468, 2021).
Hyperglycemia (continued). "Hyperglycemia-mediated oxidative stress is known to cause the nuclear translocation of NFκB, which activates the transcription of several genes coding for pro-inflammatory cytokines, like IL-6." (PMID 32630636, 2020). "Multiple studies have indicated that the levels of IL-6 are associated with hyperglycaemia and IR." (PMID 33043822, 2020). "Lastly, C5aR is constitutively expressed on Müller cells, the expression of which is up-regulated by prostaglandin E2, and most critically, hyperglycemia, and is associated with upregulation of IL-6 and VEGF leading to increased retinal endothelial cell proliferation and permeability." (PMID 31337130, 2019). "In addition, short-term acute hyperglycemia caused by refined carbohydrate intake increased circulating levels of free radicals and proinflammatory cytokines such as interleukin (IL)-6, IL-18, and tumor necrosis factor-alpha." (PMID 31167515, 2019). "Furthermore, as both chronic high-fat feeding and hyperglycemia are associated with systemic inflammation both clinically and experimentally, we assessed systemic levels of pro-inflammatory IL-6 in our respective models." (PMID 30348168, 2018). "In addition, oscillatory hyperglycemia as routinely found in most patients, causes more acute increases in plasma concentrations of pro-inflammatory cytokines including IL-6, IL-18, and TNF-α, as compared to chronic hyperglycemia." (PMID 21629436, 2010). "Similarly, genetic polymorphisms in inflammatory pathways (e.g., IL-6 promoter variants) may alter cytokine responses to hyperglycemia across ethnic groups." (PMID 41126323, 2025). "Moreover, hesperidin has been reported to decrease hs‐CRP, macrophage chemoattractant protein 1 (MCP‐1), and IL‐6 and increase the serum total antioxidant capacity, thereby preventing oxidative stress and inflammation caused by hyperlipidemia and hyperglycemia in rodents fed a high‐fat diet." (PMID 38107097, 2023). "Hyperglycaemia is known to cause immune dysfunction, adversely affecting leukocyte function and leading to the increased production and secretion of cytokines, such as IL-6, IL-1β and TNF-α, leaving diabetic patients more susceptible to infections and related comorbidities." (PMID 37627482, 2023). "Although controversy still exists whether hyperglycemia is a cause or an effect of increased IL6 expression, it is reasonable to assume that our finding of an increased leukocyte IL6 expression in both groups of GDM patients may be associated with their hyperglycemic state." (PMID 30513672, 2018). "Hyperglycemia significantly impaired macrophage phagocytosis and bactericidal activity while inducing pro-inflammatory mediator markers, IL-1, IL-6, TNF-α, and iNOS." (PMID 40001441, 2025). "Hyperglycemia induces a pro-inflammatory phenotype in macrophages, which is characterized by enhanced pro-inflammatory mediator expressions, including IL-1, IL-6, TNF-α, and NO." (PMID 40001441, 2025). "Hyperglycemia activates pro-inflammatory cytokines such as IL-6 and TNF-α, which in turn stimulate hepatic CRP production and upregulate MMP-9 expression at the site of tissue injury." (PMID 40364880, 2025). "Hyperglycemia increases the production of proinflammatory mediators, such as IL-6, IL-1β, and TNF-α, which play a crucial role in the development of chronic inflammation and thus impair immune system function." (PMID 41009326, 2025). "IL-6 is subsequently released in large quantities, promoting hepatic glucose production, inhibiting insulin release, aggravating the occurrence of hyperglycemia and triggering an inflammatory storm." (PMID 40225322, 2025). "Mechanistically, hyperglycemia, accumulation of AGEs, and elevated systemic levels of IL-6 and CRP account for endothelial dysfunction and disruption of tight junction structure, thereby compromising the barrier’s selectivity." (PMID 40806709, 2025).
Hyperglycemia (continued). "Hyperglycemia, especially under co‐culture conditions, significantly affected the secretion of IL‐6, TNF‐α, and adiponectin (p < 0.0001 for all), indicating its pervasiveness in adipokine regulation across these markers." (PMID 40746010, 2025). "During hyperglycemia, the overproduction of reactive oxygen species (ROS) triggers the release of pro-inflammatory cytokines such as IL-6, IL-1β, TNF-alpha, and IFN-γ." (PMID 39940428, 2025). "When the IL6 CC genotype is combined with ADIPOR2 GA or ADIPOR2 219 A/T, hyperglycemia is 1.3 times more frequent than with other IL6/ADIPOR2 genotype combinations." (PMID 41010061, 2025). "Our in vivo experimental study supports the role of IL-6 as its levels being elevated in STZ-induced hyperglycemia in male wistar rats and EMPA treated groups shown an amended levels of IL-6, in consistency with other studies both in vivo and in vitro." (PMID 38885232, 2024). "Follow-up investigations (e.g., HbA1C, C peptide, interleukin-6), elucidation of cytokines and antibodies involved in the immune response to COVID would be helpful in evaluation of the pathogenesis of hyperglycemia." (PMID 38350147, 2024). "The largest decrease for IL-1β, IL-6, and IL-8 was observed in normoglycemia-simulating conditions compared to both hypo- and hyperglycemia (p < 0.05)." (PMID 38542084, 2024). "Among the cytokines analyzed in this study, the levels of IL-8 and IL-6 were significantly increased in the BC in hyperglycemia, compared to both normoglycemic and hypoglycemic environments (groups I and II, respectively)." (PMID 38542084, 2024). "Our result suggests that long-term hyperglycemia for 14–16 days promotes the activation of rat astrocytes and the release of IL-6 after LPS stimulation at both 6 h and 48 h exposure to endotoxin." (PMID 38256196, 2024). "IL-6 has been shown to increase IR and induce fasting hyperglycemia by stimulating glucagon release." (PMID 39839274, 2024). "Overexpression of the miR-146a mimic can downregulate IL-6 and IL-8 in hyperglycemia/thrombin-stimulated human aortic endothelial cells (HAECs)." (PMID 38645427, 2024). "Second, IL-6 level is in line with CRD, such as COPD, with exacerbations with hyperglycemia; thus, a higher IL-6 level was found in CD." (PMID 38540106, 2024). "Hyperglycemia can contribute to tumor-related inflammation by triggering the release of pro-inflammatory cytokines such as interleukin-6 (IL-6), interferon γ (IFN-γ), tumor necrosis factor-alpha (TNF-α), and resistin." (PMID 39064000, 2024). "The biggest difference measured in samples containing different glucose concentrations was shown within the IL-6 values, which amounted to 3.67 ± 0.37 (pg/mL ± SD) for normoglycemia and were increased to 7.68 ± 0.77 in the hyperglycemia-mimicking environment." (PMID 38542084, 2024). "It is also believed to have direct anti-inflammatory effects by inhibiting nuclear factor κB (NF-κB) activation and reducing the release of inflammatory cytokines like interleukin-6 (IL-6), as well as indirectly by lowering hyperglycemia and insulin levels." (PMID 39459443, 2024). "This dysbiosis leads to reduced levels of TUDCA and CARN, which in turn alleviate their inhibition on the synthesis of IGFBP-3 and the expression of IL-6, ultimately resulting in hyperglycemia and related vasculopathy." (PMID 39206042, 2024). "The concurrent rise in IL-6 by the endothelial cells is in response to hyperglycemia, resulting in chronic inflammation." (PMID 39131026, 2024). "Research has shown that hyperglycemia can stimulate immune cells and increase pro-inflammatory cytokines such as tumor necrosis factor α, interleukin 1β, and interleukin −6 (IL-6)." (PMID 38699234, 2024). "For instance, hyperglycemia leads to the production of a wide range of pro-inflammatory factors, such as interleukin-6 (IL-6), tumor necrosis factor-α (TNF-α), and cyclooxygenase-2 (COX-2), all closely connected with pro-tumorigenic actions." (PMID 38892104, 2024).
Hyperglycemia (continued). "LPS alone stimulated the upregulation of IL-6, but in the hyperglycemia model, IL-6 was downregulated." (PMID 37467292, 2023). "In hyperglycemia condition, the excessive production of ROS lead to the release of pro-inflammatory cytokines such as IL-6, IL-1β, TNF alpha, and INFy." (PMID 37175192, 2023). "An experimental model has demonstrated that hyperglycemia can increase levels of inflammatory cytokines, including interleukin-6 and tumor necrosis factor-alpha, which play a crucial role in epithelial-to-mesenchymal transition and tumorigenesis." (PMID 37181380, 2023). "FGF-21 increased during both hypoglycemia and hyperglycemia while IL-6 and IL-10 increased during hypoglycemia." (PMID 37400734, 2023). "Our results displayed that IL-6 protein decreased during hyperglycemia implying there had been a poor immune response and LPS stimulated IL-6 expression in the contrary in both the cortex and medulla suggesting the existing of a complex mechanism." (PMID 37467292, 2023). "Although IL-6 was significantly upregulated by LPS injection compared with the model group, it was still downregulated compared with the normal group, which is interesting that IL-6 protein expression downregulated during hyperglycemia." (PMID 37467292, 2023). "(Poly)phenol metabolites quantified in lipoproteins were evaluated towards the inflammatory response of endothelial HMEC-1 cells exposed to hyperglycemia by measuring the release of IL-6 and IL-1β into the cell medium after treatment." (PMID 36516720, 2023). "In this study, intermediate hyperglycaemia caused a significant increase in CRP, TNF-α and IL-6 concentration in the PD compared to the NPD group." (PMID 38024366, 2023). "It was found that PCP was effective in suppressing hyperglycemia, hyperinsulinemia, and the expression of inflammatory cytokines (IL-6 and TNF-α), and boosting glucose tolerance in db/db mice." (PMID 37689643, 2023). "Results revealed hyperglycemia, hypoinsulinemia, increased MDA, TNF-α, IL-6, and NF-κB levels, in association with reduced CAT, SOD, GSH, Nrf2, and HO-1 levels in LCT group." (PMID 37463968, 2023). "The elevated IL-6 values found after BD confirm the hyperglycemia and the lower IRS-1 expression detected, being this myokine contributing to the general BD-IR process." (PMID 37676577, 2023). "It is well accepted that hyperglycemia leads to the expression of higher serum levels of pro-inflammatory cytokines such as interleukin-6 (IL-6), IL-8, IL-1β, and tumor necrosis factor-a (TNF-α) in women with GDM compared to normal pregnancies." (PMID 37190095, 2023). "We have also investigated the effect of hyperglycemia concomitant with LPS+Nigericin stimulation to assess the secretion of the pro-inflammatory cytokine IL-6." (PMID 37122742, 2023). "PBA notably diminished hyperglycemia-enhanced expression of TNF-α and IL-6, and elevated hyperglycemia-reduced expression of IL-10 at 0 and 6 h after reperfusion." (PMID 35289326, 2022). "We conclude that hyperglycemia compromises psoriasin through the IL-6 and YAP/TAZ pathways affecting the epithelial barrier and causing cell membrane alterations." (PMID 36127330, 2022). "Hyperglycemia can induce EPC dysfunction triggering inflammation via SDF-1β/CXCR7–AMPK pathway resulting in secretion of IL6." (PMID 36176980, 2022). "In conclusion, this study showed that 12 weeks of Eriomin supplementation, at 200 mg/d, resulted in a reduction in hyperglycemia (−5%), and a diminished inflammatory response, by decreasing blood serum markers IL-6 (−14%) and TNF-α (−20%)." (PMID 35796695, 2022). "But what is certain is the worsening of hyperglycemia and increased incidence of diabetic ketoacidosis that can be attributed to enhanced production of IL-6 and TNF-α in response to SARS-CoV-2 infection." (PMID 36778598, 2022).